RNU6-296P (RNA, U6 small nuclear 296, pseudogene)
Gene: Small nuclear RNA gene on chromosome 7 (123,457,988 to 123,458,094, reverse strand). Ensembl gene ENSG00000207338.
Homologues: Orthologues: chimpanzee U6 (100% identical), dog U6 (83% identical), pig U6 (83% identical), guinea pig U6 (78% identical). Paralogues in human: RNU6-43P (88% identical), RNU6-1216P (87% identical), RNU6-87P (87% identical), RNU6-11P (86% identical), RNU6-37P (86% identical), RNU6-38P (86% identical), RNU6-39P (86% identical), RNU6-727P (86% identical), RNU6-774P (86% identical), RNU6-812P (86% identical), RNU6-1020P (85% identical), RNU6-1124P (85% identical), and 1285 more.